EMG1 (EMG1 N1-specific pseudouridine methyltransferase)
Description:
S-adenosyl-L-methionine-dependent pseudouridine N(1)- methyltransferase that methylates pseudouridine at position 1248 (Psi1248) in 18S rRNA. Involved the biosynthesis of the hypermodified N1-methyl-N3-(3-amino-3-carboxypropyl) pseudouridine (m1acp3-Psi) conserved in eukaryotic 18S rRNA. Is not able to methylate uridine at this position. Also has an essential role in 40S ribosomal subunit biogenesis independent on its methyltransferase activity, facilitating the incorporation of ribosomal protein S19 during the formation of pre-ribosomes (By similarity). Part of the small subunit (SSU) processome, first precursor of the small eukaryotic ribosomal subunit. During the assembly of the SSU processome in the nucleolus, many ribosome biogenesis factors, an RNA chaperone and ribosomal proteins associate with the nascent pre-rRNA and work in concert to generate RNA folding, modifications, rearrangements and cleavage as well as targeted degradation of pre-ribosomal RNA by the RNA exosome.
Synonyms: C2F; NEP1; Grcc2f
Tractability: Small molecule: a structure with a bound ligand is known. PROTAC: ubiquitination databases record sites on it; its protein half-life has been measured.
Gene: Protein-coding gene on chromosome 12 (6,970,805 to 6,979,936, forward strand). Ensembl gene ENSG00000126749.
Subcellular location: Nucleus, nucleolus
Subcellular location (Human Protein Atlas): Nucleoli rim; Mitotic chromosome; Nucleoplasm
Pathways (Reactome):
Metabolism of RNA: Major pathway of rRNA processing in the nucleolus and cytosol; rRNA modification in the nucleus and cytosol
Gene Ontology:
Molecular function: identical protein binding; protein binding; RNA binding; rRNA (pseudouridine) methyltransferase activity; rRNA binding; RNA methyltransferase activity; S-adenosylmethionine-dependent methyltransferase activity
Biological process: ribosomal small subunit biogenesis; rRNA base methylation; maturation of SSU-rRNA; rRNA processing
Cellular component: nucleolus; small-subunit processome; cytoplasm; nucleoplasm; nucleus
Genetic constraint (gnomAD): Loss-of-function variants: 22 observed, 25.58 expected, observed/expected ratio (o/e) 0.86, 90% interval 0.61 to 1.23. The upper end of that interval is the gene's LOEUF score, 1.23, which puts it in group 5 of 6, group 1 being the genes least tolerant of losing a copy. Missense variants: 280 observed, 303.26 expected, observed/expected ratio (o/e) 0.92, 90% interval 0.84 to 1.02. Synonymous variants: 132 observed, 110.39 expected, observed/expected ratio (o/e) 1.2, 90% interval 1.04 to 1.38.
Gene-disease validity (ClinGen):
ClinGen rates the evidence that EMG1 causes each of these diseases.
Bowen-Conradi syndrome (autosomal recessive): Strong. Bowen-Conradi syndrome (BCS) is a lethal autosomal recessive ribosomal biogenesis disorder characterized by severe prenatal and postnatal growth retardation, microcephaly, a distinctive facial appearance, extreme psychomotor delay, hip and knee contractures and rockerbottom feet.
Homologues: Orthologues: chimpanzee EMG1 (99% identical), dog EMG1 (94% identical), pig EMG1 (93% identical), guinea pig EMG1 (92% identical), rabbit EMG1 (91% identical), rat Emg1 (91% identical), mouse Emg1 (89% identical), macaque EMG1 (84% identical), tropical clawed frog emg1 (70% identical), zebrafish emg1 (66% identical), Drosophila melanogaster CG3527 (57% identical), Caenorhabditis elegans emg-1 (52% identical).
Diseases named in the same sentence as EMG1 in open-access papers:
EMG1 is named in the same sentence as 14 diseases in open-access papers, as found by Europe PMC text mining. Sharing a sentence is not in itself a finding about the gene and the disease. The quoted sentences say what the papers report.
Bowen-Conradi syndrome (10 papers, 2010 to 2023). "Mutations in Essential for Mitotic Growth 1 (EMG1), a ribosome biogenesis factor involved in the maturation of the 18S rRNA, cause the ribosomopathy Bowen–Conradi syndrome." (PMID 32527837, 2020). "EMG1, the protein product of the gene mutated in Bowen–Conradi syndrome, has been implicated in ribosome biogenesis in yeast and human cells, although most work to determine its function has been performed in yeast." (PMID 26676230, 2014). "Mutations in EMG1 have been previously associated with Bowen-Conradi syndrome, a lethal autosomal recessive disorder." (PMID 23597238, 2013). "Further, our findings also lend support to the previous study that showed Bowen-Conradi syndrome results from a partial EMG1 deficiency." (PMID 20858271, 2010). "To begin to understand the role of EMG1 in mammalian development, and how its deficiency could lead to Bowen-Conradi syndrome, we have used mouse as a model." (PMID 20858271, 2010). "Similarly, Bowen-Conradi syndrome, a disorder characterized by bone marrow failure, developmental anomalies, and early infant death, is caused by a single point mutation (D86G) in the nucleolar RNA methyltransferase EMG1." (PMID 36790396, 2023). "Bowen–Conradi syndrome (BCS) is a lethal autosomal recessive disorder caused by a D86G substitution in the protein, Essential for Mitotic Growth 1 (EMG1)." (PMID 26676230, 2014). "Bowen–Conradi syndrome (OMIM #211180), another ribosomopathy due to recessive variants in EMG1 leading to defective ribosome biogenesis, is associated with severe developmental effects, poor growth, and physical anomalies, but interestingly not bone marrow failure." (PMID 32576952, 2020). "While replication for MLL2 was absent, one of the top pathways included EMG1, previously associated with Bowen- Conradi syndrome (pathway adjusted p-value < 0.001, gene adjusted p-value < 0.001)." (PMID 23819467, 2013). "Thus, rather than being caused by a lack of rRNA modification, Bowen-Conradi syndrome may be caused by the absence of the EMG1 protein in the nucleolus, where it normally binds and likely stabilizes the UtpB switch." (PMID 36790396, 2023).
pancreatic cancer (1 paper, 2019). "Only 10 (SCAMP1, EMG1, HCP5, TUG1, MAL2, H19, LINC00511, RP11-311C24.1, RP11-400F19.6 and CTC-459F4.3) out of 90 lncRNAs were significantly upregulated in pancreatic cancer samples when compared with normal controls." (PMID 31061236, 2019).
cancer (2 papers, 2023 to 2025). A tumor composed of atypical neoplastic, often pleomorphic cells that invade other tissues. "To highlight their relevance in cancer, we interrogated the HumanNet v3 and found that NOP56, RBM12, FKBP1A and EMG1 are highly interconnected with cancer genes and other RBPs, showing their potential to form tumorigenic RNA-regulons." (PMID 37384253, 2023). "In summary, we analyzed and integrated data from 488 COAD and 155 READ patients, 102 cancer cell lines, more than 15,000 immunostainings, and ∼10,000 raw associations between RBPs and cancer genes to unravel new RBPs involved in COAD (NOP56, NAT10, RBM12, and FKBP1A) and READ (EMG1 and CSE1L)." (PMID 37384253, 2023). "Additionally, to the best of our knowledge, no prior studies have associated FKBP1A and EMG1 with cancer before." (PMID 37384253, 2023). "Interestingly, FKBP1A and EMG1 have never been related with any of these carcinomas but presented tumorigenic features in other cancer types." (PMID 37384253, 2023).
EMG1 also shares sentences with these, for which no sentence is quoted: infection (4 papers); Stroke (2); angioedema (1); Anxiety (1); Diamond-Blackfan anemia (1); liver cancer (1); osteoporosis (1); rectal cancer (1); sarcopenia (1); Treacher-Collins syndrome (1); tumor (1).